INS (insulin)
Diseases named in the same sentence as INS in open-access papers (continued):
Sharing a sentence is not in itself a finding about the gene and the disease.
breast cancer (continued). "The variables selected by elimination for inclusion in the linear model proposed to predict the diagnosis of breast cancer were basal blood concentrations of insulin, C-peptide, HbA1c, IGF-I, cholesterol and BMI." (PMID 18665244, 2008). "We draw attention to the finding that in both pre- and post-menopausal breast cancer patients, C-peptide was significantly elevated; consequently, insulin hyperproduction occurred." (PMID 18665244, 2008). "PI3K mediates the ability of insulin growth factor to activate the Eag channel, and the ability of serum to activate the intermediate-conductance Ca2+-activated K+ channel in breast carcinoma and lymphoma cells, respectively." (PMID 19043547, 2008). "PTEN, which does not contain a D-domain sequence but does contain an FXFP motif, has been reported to inhibit insulin-stimulated ERK1/2 activation in MCF-7 epithelial breast cancer cells." (PMID 16445858, 2006). "Dual-parameter flow cytometry, following bromodeoxyuridine (BrdUrd) incorporation and propidium iodide (PI) uptake into DNA, was used to study the effects of oestradiol and/or insulin on cell cycle kinetics of human breast cancer cells in vitro." (PMID 2679851, 1989). "In line with emerging literature, our data support the role of SHBG as both a proxy marker of insulin sensitivity and exposure, hepatic function, as well as a potential diagnostic biomarker and therapeutic target in the management of PCOS, MASLD, and breast cancer." (PMID 41586225, 2025). "While its role in endometrial cancer is still elusive, evidence from breast cancer suggests that it may be involved in cellular transport and insulin signaling." (PMID 41373651, 2025). "For instance, Leptin and Insulin levels decreased, particularly in Breast cancer patients, whereas Colorectal cancer patients exhibited a reduction in pro-inflammatory cytokines such as IL-1β, IL-6, IL-8, and TNF-α, even in the absence of weight loss and bioimpedential feature changes." (PMID 41409302, 2025). "Exercise intervention could reduce the weight of breast cancer patients and improve insulin sensitivity." (PMID 41281288, 2025). "The two metabolic parameters, glucose and insulin measures, of all cancer survivors and of breast cancer survivors did not exhibit distinct associations with PA compared to those exhibited by all participants." (PMID 40937951, 2025). "Insulin-driven systemic metabolic alterations may also contribute to breast cancer pathogenesis, particularly in TNBC." (PMID 41269404, 2025). "Previous clinical data shows that reduced serum glucose and insulin levels are associated with a better prognosis of breast cancer in non-diabetic patients." (PMID 39703333, 2024). "The changes in the blood flow of skeletal muscles occurred during an oral glucose tolerance test (OGTT) despite the increased insulin levels, described by Roberts-Thompson, which could be present in obese women with breast cancer." (PMID 38397883, 2024). "Based on the 15 studies that were included, a lower risk of breast cancer (RR = 0.90, 95% CI: 0.82–0.98) was found among insulin users compared to nonusers." (PMID 38254789, 2024). "Their results demonstrated a significant increase in the risk of breast cancer mortality amongst insulin users compared to non-users (HR = 1.33, 95% CI: 1.08–1.63; p = 0.007)." (PMID 38254789, 2024). "The results of keyword clustering indicate that terms such as “in vivo,” “heart failure,” “breast cancer,” “insulin sensitivity,” “gut microbiome,” “glucose uptake,” “cardiovascular disease,” “skeletal muscle,” “insulin resistance,” and “high-fat diet” reflect research trends over the past decade." (PMID 39149117, 2024). "In other words, in postmenopausal women, obesity might implicate an increase in breast cancer development: in fact, the accumulation of additional fat tissue in women can increase breast cancer incidence due to the increase in estrogen and insulin levels." (PMID 38339271, 2024).
breast cancer (continued). "Additionally, excess insulin inhibits hepatic sex hormone-binding globulin synthesis, resulting in elevated estrogen bioactivity and promoting breast cancer progression." (PMID 38279158, 2024). "A meta-analysis of these studies indicated a statistically significant increased risk of breast cancer recurrence in insulin users vs. non-users (HR = 1.43, 95% CI: 1.13–1.80; p = 0.003)." (PMID 38254789, 2024). "Our study, with follow-up over 15 years, found no signs of increase or decrease in risk for breast cancer in postmenopausal women with T2D being treated with GLP-1RAs compared with those being treated with insulin or metformin." (PMID 38967919, 2024). "Breast cancer cells can respond to insulin, especially in diabetic patients with hyperinsulinemia." (PMID 38254789, 2024). "Additionally, it reveals that miR-122, which is highly secreted by breast cancer cells, plays a key role in suppressing glycolysis and insulin granule exocytosis in pancreatic β-cells." (PMID 38707985, 2023). "The first study also found positive associations of sedentary time with measures of adiposity (BMI, waist circumference and fasting insulin levels) in breast cancer survivors, yet these associations were weakened and non-significant when adjusting for MVPA." (PMID 36040665, 2023). "Insulin has mitotic functions in normal breast tissue and in breast cancer cells." (PMID 38156375, 2023). "Basic research revealed that long-term exposure to high insulin levels promotes breast cancer progression either directly through insulin receptor isoform A and insulin-like growth factor 1 (IGF-1) receptor activation or indirectly through alternation in the circulating estrogen levels." (PMID 36562831, 2023). "We could hypothesize that biological mechanisms involving adiposity and insulin may differ between colorectal and breast cancers or this could be related to sample size." (PMID 37096432, 2023). "However, we believe determining certain chemotherapeutic regimen can be impacted by other factors, other than breast cancer molecular subtypes, such as high glucose levels and high insulin levels." (PMID 37511575, 2023). "In addition, the target genes were significantly enriched in pathways related to PI3K/Akt, growth hormones, and insulin signalings, which are all involved in obesity-related diseases and/or breast cancer progression." (PMID 37004031, 2023). "HCC38 and MDA-MB-231 human mammary cancer cell lines were chosen so that estradiol and insulin, reagents provided in the BulletKitTM for growth of NHMECs, could be used." (PMID 37576902, 2023). "In this nested case‐control study, we found that being overweight or obese and metabolically unhealthy raises risk of postmenopausal breast cancer while overweight or obese women with normal insulin levels are not at higher risk." (PMID 37096432, 2023). "In addition, increased pancreatic insulin secretion drives alpelisib resistance in murine mammary tumor models which is overcome by dietary and pharmacological approaches that reduce insulin signaling and restore alpelisib sensitivity." (PMID 37471270, 2023). "KEGG analysis further indicated that these genes were involved in many oncogenic pathways such as the MAPK signaling pathway and insulin signaling pathway, which are attributed to several cancer types such as breast cancer, non-small cell lung cancer, colorectal cancer, and hepatocellular carcinoma." (PMID 36982338, 2023). "Additionally, obese women have higher insulin levels than normal, another hormone whose elevated levels have been connected to a variety of malignancies, including breast cancer." (PMID 37652957, 2023). "Moreover, a study in breast cancer cells has shown that insulin can also mediate mitogenic effects via both SPHK1 and SPHK2." (PMID 36979912, 2023). "Insulin, a potent mitogenic and anabolic hormone, may support breast cancer progression through the activation of MAPK and PI3K pathways that lead to many pro-tumorigenic cellular changes." (PMID 37800138, 2023).
breast cancer (continued). "Some in vivo and clinical studies suggest that indirect insulin-dependent effects may be of great significance in at least some cancers, such as breast cancer and lung cancer." (PMID 37344841, 2023). "Furthermore, the review investigates the influence of other hormones, such as insulin and growth factors, and their cross-talk with hormone pathways in breast cancer progression." (PMID 37575755, 2023). "Our findings require validation in other cohorts and with a larger number of PR- breast cancer cases but suggest that a competition between ABSI-related factors such as glucocorticoids, sex steroids, and insulin resistance determines the net outcome for the risk of individual breast cancer subtypes." (PMID 37337133, 2023). "Moreover, elevated insulin/IGF1R signaling confers drug resistance of breast cancer cells to antiestrogens." (PMID 37237509, 2023). "Insulin can also promote breast cancer via these signaling pathways." (PMID 36755926, 2023). "Besides metabolic control of cell growth by insulin and IGFs, some tumors such as prostate or breast cancer are driven by sex hormones." (PMID 35406791, 2022). "The combination of soluble breast adipocyte-derived leptin, insulin, IL-6, and TNF-α were inducers of the release of angiogenic mediators in macrophages, representing a potential mechanism for the enhanced risk of breast cancer progression in obese individuals." (PMID 35701840, 2022). "Given the phosphorylation of ER, the dynamic activation of the ER membrane complex and the role of mTOR in AMPK and insulin signalling described earlier this phosphorylation site may present a key step in the cellular response to progesterone in breast cancer." (PMID 36034422, 2022). "Use of glargine in contrast to non-glargine insulin was associated with increased risk for breast cancer and decreased risk for colon cancer." (PMID 35158824, 2022). "Our previous in vitro work demonstrated that the insulin sensitizing medication metformin could restore the chemosensitivity of human MDR breast cancer." (PMID 36077749, 2022). "Unmixing the interplay between insulin and methionine may afford targeted therapies that address the rampant lipid metabolism that facilitates breast cancer progression." (PMID 35359364, 2022). "The diverse pathophysiology of breast cancer may have important mechanisms involving methionine and insulin that can be studied with optical techniques such as spontaneous Raman spectroscopy and SRS/TPF microscopy." (PMID 35359364, 2022). "Furthermore, the inhibitory effect of ASA was found to affect insulin fibrillation and increase cellular viability in a model of insulin mediated toxicity in human breast cancer cells." (PMID 35213966, 2022). "For example, in non-diabetic breast cancer patients, higher levels of fasting insulin have been associated with a 2–threefold increased risk of mortality." (PMID 35984550, 2022). "There are several possible mechanisms explaining the critical role of visceral obesity in breast cancer prognosis, including increased circulating levels of estrogen, high circulating insulin and insulin-like growth factor 1, altered adipokine levels, and systemic and tissue-level inflammation." (PMID 36203426, 2022). "Therefore, insulin can impact on breast cancer cell growth, proliferation, and migration, which has also been proved by other studies." (PMID 36077501, 2022). "A randomised controlled trial conducted among 100 breast cancer survivors, assigned either to exercise or usual care, showed an improvement in BMI and levels of circulating biomarkers, i.e., insulin, IGF-1, adiponectin and leptin, in the exercise group after the exercise intervention." (PMID 36077690, 2022). "A small nonrandomized study of 23 women at increased risk for breast cancer found that IF for 2 days per weeks resulted in 4.8% reduction in body weight, an 8.0% reduction in body fat, and an improvement in insulin resistance over 4 to 5 weeks." (PMID 35984550, 2022).
breast cancer (continued). "Furthermore, ST18 plays a variety of other roles, such as inhibiting breast cancer cells, regulating TNFα, inducing pancreatic β-cell apoptosis, and impairing insulin secretion; however, many of its biological functions have not yet been determined." (PMID 35783123, 2022). "Furthermore, glucose and other factors involved in glucose metabolism such as insulin and insulin like growth factors enhance breast cancer cell proliferation and contribute to breast cancer development." (PMID 35917304, 2022). "Moreover, high insulin level is independently associated with breast carcinogenesis and progression, and this is supported by reports of insulin overexpression in breast cancer cells." (PMID 34225729, 2021). "Pisani in her meta-analysis showed that increased levels of C-peptide or endogenous insulin are associated with an increased risk of pancreatic, colorectal, and breast cancer, but not endometrial cancer." (PMID 33562380, 2021). "Another study indicated that changes in insulin levels and/or changes in body fat or fat deposition by exercise may mediate breast cancer prognosis in part." (PMID 35096970, 2021). "Previous studies showed that EV-transmit miRNAs effectively modulated cell signaling in recipient cells, for instance, breast cancer-secreted miR-105 promoted metastasis, and macrophages utilized exosomal miRNAs to regulate insulin sensitivity in adipose tissue." (PMID 33726799, 2021). "Secondly, UA only explained part of the association between BMI and postmenopausal breast cancer; some other important factors like the levels of free estradiol and insulin may also link adiposity with breast cancer, and their roles need further explorations." (PMID 35185779, 2021). "Besides, elevated insulin and glucose levels have been observed in patients with early-stage breast cancer exhibiting white adipose tissue inflammation." (PMID 34456877, 2021). "It has also been reported that hyperinsulinemia increases the risk of breast cancer irrespective of the body mass index (BMI), and so it can be postulated that insulin is associated with breast cancer." (PMID 34552932, 2021). "Other diabetic treatments include externally administrated insulin, which is known for its mitogenic effects, and has been associated with a non-significant increased risk of breast cancer." (PMID 34225729, 2021). "We reviewed the main findings recent years on the principal molecular actors that are involved in the interactions between MetS and breast cancer biology, including leptin, adiponectin, insulin and IGF-1, Angiotensin II and Calcium and, cholesterol and lipoprotein." (PMID 33842335, 2021). "Additionally, diabetes can directly affect breast cancer by altering related molecules, such as insulin, IGF-1 and inflammatory markers." (PMID 33842335, 2021). "Notably, DDR1 enhanced breast cancer cell proliferation, migration, and colony formation in response to insulin and IGFs." (PMID 34206590, 2021). "Serum insulin levels are increased in nondiabetic overweight breast cancer patients, and this is a risk factor for breast cancer development." (PMID 32133259, 2020). "The association between serum insulin level and breast cancer deaths was not statistically significant." (PMID 33180852, 2020). "Taken together, these studies provide evidence that activation of AKT-signaling is an adverse prognostic factor in breast cancer and support the rational for normalizing insulin-driven PI3K/AKT/mTOR-signaling pathway in women with breast cancer and woman at risk for breast cancer." (PMID 32153503, 2020). "One of the strongest risk factors for breast cancer is high breast cancer density; along with other factors, insulin treatment associated with mammographic density does not imply increased breast cancer risk." (PMID 32528752, 2020).
breast cancer (continued). "PFK1 has been considered as a potential regulator of skeletal muscle insulin sensitivity and altered insulin-stimulated glucose metabolism, and differential expression of phosphofructokinase-1 isoforms also correlates with the glycolytic efficiency of breast cancer cells." (PMID 32104690, 2020). "Insulin analogue X10 has a higher mitogenic potency than native human insulin in vitro and supra-pharmacological doses of insulin X10 increased the incidence of mammary tumours in rats." (PMID 32350367, 2020). "A recent study has shown that the insulin-dependent increase in the expression of T-bet in breast tumors is associated with a subsequent decrease in the expression of GATA3, followed by resistance to hormonal therapy in human ER+ breast cancer." (PMID 32225066, 2020). "The national prospective observational study demonstrated that the serum C-peptide level was associated with increased breast cancer deaths, and further analyses showed that the association was independent of insulin level." (PMID 33180852, 2020). "These high insulin levels may contribute to the development of breast cancer subtypes that carry a poor prognosis." (PMID 32393319, 2020). "Nuclear receptor subfamily 2, group F, member 2 (NR2F2) has been implicated in the development of breast cancer, however its contribution to insulin-induced EMT in breast cancer remains unclear." (PMID 32631390, 2020). "Breast cancer has also been found associated with elevated levels of endogenous circulating insulin in non-diabetic patients." (PMID 32631390, 2020). "Further, insulin promotes breast cancer cell proliferation and migration." (PMID 32631390, 2020). "In addition, after exercise interventions, breast cancer patients have reduced fasting insulin levels due to the reductions in body weight, anticipating better prognosis of breast cancer." (PMID 33108715, 2020). "In conclusion, the present study indicated that serum C-peptide level is associated with increased risk of breast cancer death, and it is independent of insulin level." (PMID 33180852, 2020). "Of 44 single-nucleotide polymorphisms (SNPs) with GTs, 38 fasting-glucose and 6 fasting-insulin SNPs showed heterogeneous associations with breast cancer, without significant directional pleiotropy observed." (PMID 33193614, 2020). "For users of glargine insulin compared to users of non-glargine insulin, a decreased risk of colon cancer, as well as a marginally significant increased risk of breast cancer and prostate cancer, was observed." (PMID 33585194, 2020). "BBR lowers blood sugar, increases insulin sensitivity, and corrects lipid metabolism disorders; it may reduce the incidence of breast cancer." (PMID 31208348, 2019). "In addition, women with serum insulin levels in the upper tertile are more than twice as likely to develop breast cancer." (PMID 31555644, 2019). "Among insulin users, a slightly higher incidence of breast cancer was observed." (PMID 30895533, 2019). "Therefore, it is of great importance to gain more insight into the effects of pre-operative carbohydrate administration in breast cancer regarding insulin-related characteristics, proliferation, and clinical outcomes." (PMID 31703648, 2019). "In addition, activated insulin and IGF-I receptors were detected in all breast cancer subtypes and associated with poor survival in patients." (PMID 30634494, 2019). "The present study supports the hypothesis that adjuvant metformin or other insulin-lowering therapeutic interactions may have their greatest effect in breast cancer patients with ER-positive T2 tumors." (PMID 31703648, 2019). "Nevertheless, the observed risk continued fairly unchanged by adjustments for BMI, signifying that the influence of insulin on breast cancer risk was not related to excess weight." (PMID 31292496, 2019). "In breast cancer patients without diabetes, high insulin levels have been associated with a poor prognosis." (PMID 31703648, 2019).